INS (insulin)
Diseases named in the same sentence as INS in open-access papers (continued):
Sharing a sentence is not in itself a finding about the gene and the disease.
diabetes (continued). "The decision to initiate insulin therapy in diabetic patients should consider various aspects, like the presence of symptoms typical of diabetes, blood glucose levels, presence of catabolic signs, and C-peptide values." (PMID 35407442, 2022). "Diabetes mellitus is a group of metabolic disorders that are characterized by high blood glucose levels over prolonged periods of time resulting from insulin resistance, inability to produce insulin or both." (PMID 35744874, 2022). "An example is the inhalable drug Afrezza® (human insulin), a inhalation insulin powder for patients with diabetes requiring prandial insulin." (PMID 36432681, 2022). "C. myrrha can treat the diabetes mellitus and the resin solution stimulates insulin secretion, and anti-microbial activity, human heterophyiasis with the gastro-intestinal troubles with parasitosis." (PMID 36188609, 2022). "This eventually leads to hyperglycemia, insulin resistance, and an imbalance in insulin secretion, and if disease progression is severe, diabetes-related complications can occur in the heart, kidneys, blood vessels, eyes, and nerves." (PMID 36355487, 2022). "CDKAL1, as a mechanism-related protein for diabetes, is related to the defects of proinsulin conversion and insulin response under glucose stimulation." (PMID 36183068, 2022). "The variation in knowledge is about the same for the areas of diet (13–49%) and glycemic control (13–55%), while it is less in diabetes-related complications (29–52%) and insulin users (2–5%)." (PMID 36527016, 2022). "Because of its importance in macronutrient metabolism, PPAR‐γ is a promising target for synthetic insulin sensitizers such as thiazolidinediones in the treatment of type 2 diabetes mellitus." (PMID 36200185, 2022). "Before insulin was available, the most common dietary treatment for diabetes mellitus was a high-fat, low-carbohydrate diet." (PMID 35536220, 2022). "Diabetes is a metabolic and endocrine illness set apart by hyperglycemia and glucose narrow-mindedness because of insulin opposition." (PMID 35268815, 2022). "We further tested C646’s effect on insulin signaling in hepatocytes from mice with obesity and diabetes." (PMID 35074429, 2022). "Apart from glucotoxicity, the increase in free fatty acids (FFAs) in insulin-resistant states such as diabetes and obesity leads to oxidative stress and lipotoxicity through several pathways." (PMID 36289641, 2022). "We examined the retinal microvascular changes and associated factors in type 2 diabetes mellitus (T2DM) before and after intensive insulin therapy." (PMID 35459162, 2022). "We have reported that almost two thirds of persons with longstanding diabetes, included in our study, estimated their prandial insulin need inappropriately, resulting in hypoglycemia or hyperglycemia." (PMID 36619534, 2022). "One post expressed the same feeling of reliance and helplessness by relating diabetes with a voodoo doll controlled by strings in the hands of the disease and thinking of oneself as an insulin junkie for life." (PMID 36141360, 2022). "Insulin sensitivity and diabetes progression are closely related to the modulation of gut microbial composition." (PMID 36465607, 2022). "Hyperglycemia is a condition known for the impairment of insulin secretion and is responsible for diabetes mellitus." (PMID 35844378, 2022). "First-line drugs, such as metformin, are generally introduced to manage early diabetes and subsequently more aggressive and more combinations of drugs are then added as the diabetes progresses and eventually insulin is used when all pancreatic reserve is lost." (PMID 35574035, 2022). "Lower AST/ALT and higher INS*PA were also able to predict obesity, hypertriglyceridemia, and diabetes mellitus in older subjects." (PMID 35370985, 2022). "Type 2 diabetes mellitus (T2DM) is a complex metabolic disorder characterized by hyperglycemia resulting from the impairment of insulin secretion or cell tissue resistance to insulin action." (PMID 35012531, 2022).
diabetes (continued). "Diabetes is a disease affecting more than 537 million individuals and the only way to control the blood glucose level is to use insulin." (PMID 36462118, 2022). "The findings will help design patient-centered interventions to promote adherence to insulin in this age group, and guide patients’ consultations and diabetes self-management education (DSME) programs." (PMID 35673417, 2022). "The increasing diversity of diabetes medications including insulin can make it difficult for nurses and midwives to maintain up-to-date knowledge and provide safe and high-quality care." (PMID 36068537, 2022). "Combining an insulin pump and continuous glucose monitor with a control algorithm to deliver insulin is an alternative to patient self-management of insulin doses to control blood glucose levels in diabetes mellitus patients." (PMID 36099285, 2022). "Diabetes mellitus (DM) is a disorder characterized by persistent elevated levels of blood glucose, consequences of impaired insulin production, resistance or both." (PMID 35723349, 2022). "Diabetes mellitus is one of the most common metabolic disorders worldwide, resulting from a defect in insulin secretion, insulin action or both." (PMID 36236669, 2022). "Although there were some adverse effects of insulin preparations and some obstacles were there for a patient with diabetes for insulin delivery, with advancements, scientists were able to reduce such negative impacts." (PMID 35723344, 2022). "This will facilitate the promotion and application of intelligent insulin delivery systems in the treatment of diabetes, such as subcutaneous embedding, intravenous injection, and oral delivery." (PMID 35268787, 2022). "Diabetes mellitus (DM) is a chronic metabolic disease characterized by insufficient insulin secretion from pancreatic β cells and leads to high blood glucose levels." (PMID 35327551, 2022). "Apart from the impairments in brain insulin production and signaling, additional conditions are found at the intersection of diabetes and AD, such as oxidative stress and the formation of advanced glycation end products." (PMID 36232867, 2022). "A VLCKD reduces glucose and insulin levels, improving insulin sensitivity and leading to an improvement in glycaemic control for patients with type 2 diabetes mellitus and an improvement in gonadal function in women (PCOS)." (PMID 35745118, 2022). "The diabetic AAA patients all received treatment for diabetes, and one out of six received insulin therapy." (PMID 35208203, 2022). "Insulin is still the first line therapy at the onset of diabetes even if new drugs are appearing on the scientific landscape of this complex syndrome." (PMID 35270448, 2022). "Protein tyrosine phosphatase 1B (PTP1B), a major negative regulator of the insulin-signaling cascade, is a promising therapeutic target for diabetes." (PMID 35082907, 2022). "Excessive ubiquitination caused by genetic variants of rs10009742 in MARCHF1 impairs the activity of cellular insulin by degrading insulin receptor-β on the cell surface, leading to diabetes." (PMID 36422279, 2022). "Diabetes mellitus is a type of metabolic disease characterized by high blood glucose, with insulin secretion defect or biological damage acting as its major reason of pathogenesis." (PMID 35936373, 2022). "A small number of experimental and cohort studies have documented that S-Equol can improve diabetes symptoms by regulating the gut microbiota and metabolites and ameliorating insulin secretion failure." (PMID 36337646, 2022). "Intraperitoneal injection of STZ can directly destroy the islet β cells of rats, resulting in the disturbance of insulin signal transduction and glucose metabolism, and the characteristics of diabetes in rats." (PMID 35368764, 2022).
diabetes (continued). "In diabetes, oxidative stress leads to reduced insulin production, impaired insulin secretion, β-cell dysfunction and its apoptosis, reduced expression of the GLUT-4 receptor and impairment of the insulin signal transduction pathway." (PMID 36555387, 2022). "In the future we propose to extend these analyses to include insulin-induced hypoglycemia, because of the important adverse consequences of hypoglycemia on the long-term management of diabetes mellitus." (PMID 36548717, 2022). "Other studies have shown that CGA can decrease fasting blood glucose (FPG) level and promote insulin secretion in patients with impaired glucose tolerance to alleviate diabetes." (PMID 35845802, 2022). "Eighteen exposures were investigated in relation to obesity and fewer associations with the other outcomes were reported (blood pressure [n = 9]; glucose, insulin or diabetes [n = 4]; lipids [n = 5]; and MetS [n = 5])." (PMID 35954531, 2022). "There are many possible pathways that have been proposed to connect diabetes and cancer, including an increase in insulin/IGF-1 signaling, lipid and glucose uptake and metabolism, alterations in the profile of cytokines and chemokines." (PMID 35976968, 2022). "Patients with this condition will eventually develop diabetes, presenting a variable response to insulin-sensitizers, such as metformin and thiazolidinediones, and high doses of insulin." (PMID 35498407, 2022). "The East Africa Diabetes Study Group (EADSG) recommended keeping the insulin in use at room temperature (20–25 °C) for 6 weeks, avoiding sunlight, and for 4 weeks if the temperature goes up to 30 °C." (PMID 35443846, 2022). "The model was adapted to gender, age, diabetes duration, year of treatment, migration, type of insulin treatment, degree of urbanization, and socioeconomic index." (PMID 36290631, 2022). "Metformin is the most commonly used treatment to increase insulin sensitivity in insulin-resistant (IR) conditions such as diabetes, prediabetes, polycystic ovary syndrome, and obesity." (PMID 35163187, 2022). "Participants in Group C (≥12 NSHEs per year) had a longer duration of diabetes and were less likely to be insulin naive." (PMID 34704120, 2022). "Inadequate diagnosis and treatment of diabetes is likely to be major contributor to these early deaths, highlighting the urgent need to provide better access to insulin and basic diabetes education and care." (PMID 35143780, 2022). "Here we report a role for NCC- and IL18r-mediated IL18 activities in BAT thermogenesis and WAT insulin sensitivity that mitigates obesity and diabetes." (PMID 36482059, 2022). "The basic diabetes skills and tasks are as important, or even more important, with hybrid closed-loop therapy than with standard insulin therapy and should be reinforced." (PMID 32914648, 2022). "In this condition, diets that stimulate insulin secretion to lead to long-term insulin exposure and the development of metabolic diseases such as type 2 diabetes mellitus and prediabetes." (PMID 36585722, 2022). "The authors explain that adiponectin is related to insulin sensitivity, and thus, increased blood concentrations are beneficial to individuals with diabetes." (PMID 35758833, 2022). "Diabetes mellitus is an endocrine disorder that affects glucose metabolism, making the body unable to use the insulin it produces effectively." (PMID 36557487, 2022). "Low carbohydrate diets are effective in remission of diabetes and improve insulin sensitivity as measured by HOMA-IR." (PMID 35677551, 2022). "Since insulin is prescribed to patients with more advanced diabetes mellitus, an earlier diagnosis of CHD allows for early intervention and the potential early diagnosis of other cardiovascular complications, thus improving their overall survival." (PMID 36556321, 2022). "Subgroup D had the highest fasting glucose, TyG and TC levels, and more diabetes pills and insulin use." (PMID 35948978, 2022).
diabetes (continued). "Several case studies have reported children with T1D who are overweight or obese becoming resistant to their exogenous insulin and developing “double diabetes,” explained as a pattern of increasing insulin resistance on a background of insulin-requiring T1D." (PMID 35342770, 2022). "As stated, C4 was composed of women with complications during pregnancy (including hypertension and gestational diabetes) and C5 gathered diabetics who mainly consumed insulin." (PMID 36064616, 2022). "Diabetes Mellitus (DM) is a metabolic disorder resulting from a disturbance of insulin secretion, action, or both." (PMID 35336756, 2022). "Being an employee, taking insulin for a long time, having a good prevention practice, and having a type of diabetes mellitus were strongly correlated with practicing hypoglycemia prevention." (PMID 36318542, 2022). "First, related to the studied conditions, diabetes was undisputedly the most studied; probably due to the need for positioning new forms of insulin administration." (PMID 36120091, 2022). "In patients with T1 and T2 diabetes, a cluster of insulin-resistant individuals has been found to have a significantly higher risk of developing DKD." (PMID 35550634, 2022). "After 21 days of KD in diabetes patients, glucose and insulin levels significantly were reduced with high BHB levels in serum." (PMID 35572519, 2022). "Recent studies have documented the link between high body mass index (BMI) and diabetes via proinflammatory cytokines, insulin resistance, increased levels of circulating fatty acids, and impaired cellular metabolism." (PMID 36010180, 2022). "Although we excluded patients with diabetes mellitus, we cannot exclude the possibility of pre-existing impaired insulin sensitivity in women." (PMID 35160299, 2022). "Decreased PLP has been observed to be correlated with an increased rate of diabetes due to potential alterations in enzymes related to disturbed insulin activity." (PMID 36430529, 2022). "In the Diabetes Control and Complication Trial, 1441 patients with type 1 diabetes (T1D) were randomized to receive intensive or conventional insulin treatment." (PMID 35528010, 2022). "Other factors selected (at P‐value < .005) were transient ischemic attack in trial and diabetes, insulin use and low‐density lipoprotein cholesterol at baseline." (PMID 36092692, 2022). "In diabetes, where either insulin production or sensitivity is impaired, the blood glucose level rises." (PMID 35153824, 2022). "The OPACH study estimated a HR of 0.88 (95% CI 0.78, 1.00) between steps/day and diabetes defined by self-report of physician diagnosed diabetes requiring the need of insulin or hypoglycemic medication." (PMID 35428253, 2022). "Preliminary case reports also confirmed the findings that pyruvate protected against diabetes by reducing daily insulin doses in type 1 diabetes." (PMID 35991638, 2022). "The diagnosis of LADA is generally based on the presence of autoantibodies (mainly GAD autoantibody) at diabetes diagnosis, age >30 years old at diabetes onset and at least 6 months between the time of diagnosis and initiation time of insulin treatment." (PMID 35616612, 2022). "Diabetes is a long-term metabolic disease in which the impaired ability of the body produce and/or respond to the hormone insulin." (PMID 35620114, 2022). "Self-reported diabetes was classified as T1D if: diagnosis age ≤ 40 years and has been receiving insulin treatment since less than one year after diagnosis." (PMID 36078596, 2022). "A recent study showed that a diabetes animal model exhibits hypothyroidism, increased inflammatory responses, and reduced insulin sensitivity." (PMID 35328405, 2022). "Indeed, although lower body weight in patients who have diabetes has been correlated with the recovery of the caloric balance promoted by glucose excretion, it is also associated with the positive effects of SGLT2i on adipose tissue mass; indeed, its reduction is able to boost insulin sensitivity." (PMID 36145112, 2022).
diabetes (continued). "Several researchers have indicated that artichoke promotes insulin secretion, sensitivity, and plasma glucose reduction in animal models of diabetes." (PMID 35186807, 2022). "Reports also suggested that COVID-19 lockdown negatively affected weight and glucose control in individuals with diabetes, mainly in patients on insulin." (PMID 35875025, 2022). "Endothelial dysfunction is not only a consequence of insulin resistance but also impairs insulin signaling to further reduce insulin sensitivity, thereby resulting in a destructive cycle in metabolic disorders and diabetes." (PMID 36358485, 2022). "“Smart” insulin pens, which capture data on insulin dosing and incorporate this information with glucose excursion data from glucose monitors and connect wirelessly to diabetes management software, are suitable for people on insulin injections." (PMID 34922811, 2022). "A metaanalysis study showed a good clinical efficacy of stem cell-based therapy of diabetes with documented results of reduction of insulin dosage or even insulin independence." (PMID 34510360, 2022). "The multiple quantile regression analysis confirmed the independent effect of obesity, alone or associated with diabetes, and gender on plasma CNTF levels; in addition, fasting insulin was positively associated with plasma CNTF, with higher levels in females." (PMID 35585213, 2022). "The major findings were correlations with insulin levels and hip/waist ratio in specifics CpGs in newly diagnosed diabetes and pre-diabetes." (PMID 35225959, 2022). "The post-lifetime analyses confirmed that HFD-treated animals developed signs of metabolic syndrome and diabetes mellitus—increased levels of glucose, insulin, and cholesterol." (PMID 36555360, 2022). "Type1 DM (T1DM) or insulin-dependent diabetes mellitus (IDDM) mainly refers to a state where insulin levels are extremely low due to autoimmune targeting and destruction of beta cells (ADA, 2017)." (PMID 35368460, 2022). "Multiple studies have shown that BBR can not only reduce hyperglycaemia, regulate dyslipidaemia and attenuate kidney inflammation but also improve insulin resistance and enhance insulin activity in an animal model of diabetes." (PMID 35001506, 2022). "Diabetes mellitus (DM) is a chronic metabolic disease characterized by elevated blood glucose levels resulting from impaired insulin secretion/action and glucose homeostasis." (PMID 36418969, 2022). "While there is an emerging role of pancreatic fat in the aetiology of type 2 diabetes mellitus (T2DM), its impact on the associated decrease in insulin secretion remains controversial." (PMID 36584200, 2022). "While being treated inpatient for the foot ulcers, the patient adamantly and repeatedly refused to receive standard hospital diabetes management with short- and long-acting insulin." (PMID 35251838, 2022). "In vivo, SN-401 restores glycemic control, reduces hepatic steatosis/injury, improves insulin-sensitivity and insulin secretion in murine diabetes." (PMID 35145074, 2022). "The carbohydrate-insulin ratio is a static value determined by the person with diabetes and the doctor regarding the amount of insulin to give for an amount of carbohydrates at a particular time of the day." (PMID 36992757, 2022). "People requiring insulin were younger, had a higher preadmission HbA1c, were more frequently on oral medication for diabetes before the admission, and were more likely to be obese (body mass index ≥30 kg/m2), with p ≤ 0.001 for all." (PMID 35256883, 2022). "Type 2 diabetes (T2D) is the most common type of diabetes, especially in adults, which is characterized by insulin resistance and/or insufficient insulin secretion." (PMID 35057558, 2022). "Type 1 diabetes mellitus occurs when the pancreatic β-cells that produce insulin are destroyed by the immune system, necessitating lifelong insulin therapy." (PMID 35591319, 2022).